GAS5 (growth arrest specific 5)
Diseases named in the same sentence as GAS5 in open-access papers (continued):
Sharing a sentence is not in itself a finding about the gene and the disease.
breast carcinoma (continued). "Breast cancers showed a significantly lower GAS5 expression compared to normal breast epithelial tissues, low expression can induce growth arrest and apoptosis independently of other stimuli in breast cancer cell lines." (PMID 29296179, 2017). "Nucleofection of hormone-sensitive and –insensitive breast cancer cell lines with a GAS5 HREM DNA oligonucleotide increased both basal and ultraviolet-C-induced apoptosis, and decreased culture viability and clonogenic growth, similar to GAS5 lncRNA." (PMID 26862727, 2016). "In some prostate and breast cancer cell lines, expression of GAS5 induces growth arrest and apoptosis independent of other stimuli." (PMID 26735578, 2016). "GAS5 lncRNA is a decoy of glucocorticoid/related receptors; a stem-loop sequence constitutes the GAS5 hormone response element mimic (HREM), which is essential for the regulation of breast cancer cell apoptosis." (PMID 26862727, 2016). "GAS5 expression was downregulated in all HER2-positive breast cancer specimens (n = 20) relative to pair-matched noncancerous tissues." (PMID 27034004, 2016). "We determined GAS5 expression in 86 pairs of breast cancer tissues and corresponding non-tumor tissues by qRT-PCR analysis." (PMID 27034004, 2016). "For breast cancer and HNSCC, low GAS5 expression is an adverse prognostic factor for survival." (PMID 24884417, 2014). "Reducing chemoresistance by targeting signaling pathways highlights its therapeutic potential.Although the expression of GAS5 has been investigated in a number of human cancers, such as breast cancer and lung cancer, its pan-cancer expression pattern is not well-characterized." (PMID 39958058, 2025). "Furthermore, biological function experiments showed that GAS5 suppressed breast cancer growth via IGF2BP2/QKI, and this inhibitory effect was modulated by FTO both in vitro and in vivo, thus representing a promising strategy for the treatment of breast cancer." (PMID 38782769, 2024). "Also, we examined the expression of GAS5 in breast cancer tissues and in the corresponding adjacent noncancerous normal tissues by qRT-PCR." (PMID 38782769, 2024). "In addition, GAS5 expression is suppressed by promoter methylation in triple-negative breast cancer (TNBC), suggesting that lncRNAs play key roles in aggressiveness of breast cancer." (PMID 36810560, 2023). "In contrast, while overexpressed GAS5 can strengthen ADR sensitivity in vivo and in vitro, GAS5 acted as a sponge to miR-221-3p and subsequently drove the expression of dickkopf 2 (DKK2), which ultimately inactivated the Wnt/β-catenin pathway to weaken ADR resistance in breast cancer cells." (PMID 36613528, 2022). "Moreover, GAS5 and PTEN levels were positively correlated in breast cancer cell lines." (PMID 34202777, 2021). "In addition, the expression of GAS5 is significantly downregulated in breast cancer tissues compared with adjacent non-cancerous tissues." (PMID 34527584, 2021). "Therefore, GAS5 activates the Wnt/β-catenin signaling pathway via the GAS5/miR-221-3p/DKK2 axis and may be used to enhance the sensitivity of breast cancer patients to ADR treatment." (PMID 34202777, 2021). "In addition, the authors showed that the inhibitory effect of GAS5 on miR-21 expression in HER2-positive breast cancer cell lines led to activation of the miR-21 target, PTEN mRNA, and establishment of the GAS5/miR-21/PTEN axis in breast cancer." (PMID 34202777, 2021). "Interestingly, the GAS5 GRE-mimic alone can increase apoptosis in breast cancer cells, suggesting that the oligonucleotides of the GRE-mimic may be applicable to breast cancer therapy." (PMID 32486413, 2020). "The results obtained in the present study indicate that sorafenib mediated the up-regulation of GAS5 and the down-regulation of HOTTIP and HOXA-AS2 in most HCC, renal and breast cancer cells and probably their expression modulation may lead to a less aggressive cancer phenotype of the cells." (PMID 31235746, 2019).
breast carcinoma (continued). "Furthermore, they found that GAS5 expression was also down-regulated (∼2.0-fold) in HER-2 positive breast cancer samples (n = 20) relative to matched noncancerous tissue samples." (PMID 29299178, 2017). "While the GAS5 HREM interacts with progesterone receptor, this interaction is unlikely to play a major role in breast cancer cell survival, since both GAS5 lncRNA and the GAS5 HREM sequence induce apoptosis in TNBC cells which are devoid of progesterone receptors." (PMID 26862727, 2016). "Consistently, miR-21 and GAS5 showed negative correlation in breast cancer specimens." (PMID 24013378, 2013). "The expression levels of GAS5 were found to be increased in almost all the cancer cells treated with sorafenib compared to cells exposed to DMSO (except SKHep1C3) proving that sorafenib may up-regulate GAS5 not only in different HCC cell lines but also in renal and breast cancer cells." (PMID 31235746, 2019). "Hence, given the broad context of the GAS5 anti-cancer properties, future therapies that augment or rescue expression of this lncRNA might have broad relevance not just in breast cancer, but in multiple cancers." (PMID 31533355, 2019). "Moreover, there was a negative correlation between the expression of GAS5 and FTO in breast cancer tissues and cells." (PMID 38782769, 2024). "Similarly, overexpression of another member of the GAS family, GAS5, did not change the cell cycle distribution of the MCF-10A human breast cancer cell line and a mouse thymoma cell line." (PMID 26506240, 2015).
colorectal cancer (75 papers, 2014 to 2025). A primary or metastatic malignant neoplasm that affects the colon or rectum. "Recently, the GAS5 gene encoded LncRNA termed Growth arrest-specific 5 (GAS5) was found to act as a tumor suppressor in prostate, breast, lung, and colorectal cancers." (PMID 37858151, 2023). "The growth arrest special 5 (GAS5), as a research hotspot of long noncoding RNAs (lncRNAs), has been reported to be associated with colorectal cancer (CRC)." (PMID 30902880, 2019). "Growth arrest-specific 5 (GAS5), a LncRNA encoded by the GAS5 gene, is recently identified as a tumor suppressor in several cancers such as lung, breast, prostate and colorectal cancers." (PMID 31673232, 2019). "In current study, we investigated the possible association between susceptibility of lung cancer and GAS5 rs145204276, which showed contradictory roles in carcinogenesis of colorectal cancer and hepatocellular carcinoma." (PMID 29207621, 2017). "Besides, GAS5 polymorphism has been shown to have an opposing effect in cancers such as hepatocellular carcinoma, colorectal cancer, and oral cancer, where higher GAS5 expression has been linked to an increased risk of cancer." (PMID 35736636, 2022). "Growth arrest-specific transcript 5 (lncRNA GAS5) promotes Yes1-associated transcriptional regulator (YAP) degradation via the ubiquitin-proteasome pathway by interacting with the WW domain of the YAP protein in colorectal cancer." (PMID 32429086, 2020). "Negatively controlled by YTHDF3, the lncRNA GAS5 could restrain colorectal cancer progression by causing YAP (Yes1 associated transcriptional regulator) phosphorylation and degradation." (PMID 32793593, 2020). "In addition, patients with low levels of GAS5 mRNA have a shorter survival time, and statistical studies have found that the expression level of GAS5 can be an independent risk factor for colorectal cancer and a predictor of prognosis." (PMID 30606744, 2019). "mTOR signaling pathway suppresses the expression of GAS5 and establishes a feedback mechanism with miR-34a in colorectal cancer cells to mediate CRC cell macroautophagy." (PMID 39830506, 2024). "It was found that lncRNA GAS5 suppresses the proliferation and migration of colorectal cancer cells and triggers apoptosis through its interaction with miR-10b." (PMID 39830506, 2024). "We found that TSGs (e.g., DKK1 and GAS5) in colorectal cancer with hypermethylated promotors were re-activated and two oncogenes (i.e., EREG and MALAT1) were down-regulated upon 5-AZA-CdR treatment." (PMID 36882403, 2023). "A targeted PCR-based approach demonstrates that circulating GAS5 and hsa-miR-221 detected in the blood plasma as well in the exosomes are valuable for the colorectal cancer prognosis." (PMID 37569782, 2023). "YTHDF3 also has been indicated to bind to m6A-modified LncRNA GAS5 and facilitate LncRNA GAS5 degradation in a methylation-dependent manner, indicating a new insight into LncRNA GAS5 in colorectal cancer progression." (PMID 37365581, 2023).
colorectal cancer (continued). "The expression levels of circulating hsa-miR-221 and GAS5 were associated with the TNM stage, metastases, and other clinical characteristics of patients with colorectal cancer." (PMID 37569782, 2023). "GAS5 (Growth Arrest Specific 5): The long noncoding RNA GAS5 has been found to be a key regulator in the context of colorectal cancer (CRC) and is known to play a vital role in the suppression of colorectal carcinogenesis." (PMID 37760852, 2023). "In colorectal cancer, LncRNA GAS5 interacts with the WW structure of YAP, promotes its phosphorylation and ubiquitin mediated degradation, and promotes the transfer of endogenous YAP from nucleus to cytoplasm." (PMID 35022030, 2022). "A study in colorectal cancer showed that GAS5 can inhibit cell proliferation and promotes apoptosis by upregulating FOXO3a expression via sponging miR-182-5p." (PMID 35736636, 2022). "To explore the role of GAS5 in the development of CRC, we first investigated the expression of GAS5 in 53 colorectal cancer (CRC) patient's specimens." (PMID 36062165, 2022). "GAS5 is a specific expression of lncRNA in colorectal cancer, which is abnormally high in colorectal cancer tissues." (PMID 36062165, 2022). "In this study, we studied the biological function of GAS5 in colorectal cancer and explored the potential mechanisms of cell migration, metastasis, and invasion mediated by GAS5." (PMID 36062165, 2022). "M6A reader YTHDF3 negatively regulates the long non-coding RNA GAS5, inhibiting the progression of colorectal cancer by interacting with and triggering YAP phosphorylation and degradation." (PMID 35187083, 2022). "The expression of GAS5 in 53 paired normal and colorectal cancer tissues and colorectal cancer cell lines was detected by real-time PCR." (PMID 36062165, 2022). "GAS5 is abnormally high in colorectal cancer tissues, which is a specific expression of lncRNA in colorectal cancer (CRC)." (PMID 36062165, 2022). "The capacity of migration in CRC was also significantly inhibited by GAS5 upregulation, and inhibition of GAS5 expression also significantly promoted the migration of colorectal cancer cells." (PMID 36062165, 2022). "We found that GAS5 was significantly downregulated in colorectal cancer specimens and in metastasis specimens compared with adjacent nontumor/nonmetastasis tissues." (PMID 36062165, 2022). "It is found that m6A modification in GAS5, a tumor suppresser, would lead to GAS5 degradation via binding to m6A reader YTHDF3 in colorectal cancer (CRC), which further results in the decreased expression of YAP." (PMID 34603397, 2021). "For instance, in colorectal cancer, GAS5 blocks disease progression through inducing YAP phosphorylation and degradation." (PMID 34022918, 2021). "lncRNA GAS5 negatively regulated by YTHDF3 (reader) was demonstrated to be a tumor-suppressor in colorectal cancer." (PMID 34238292, 2021). "In other reports, the GAS5 rs55829688 T>C polymorphism has been shown to alter YY1 binding to this promoter region, thereby impairing GAS5 expression and reducing the risk of colorectal cancer development." (PMID 33937403, 2021). "But, in colorectal cancer, lower levels of GAS5 triggers the transcription of YTHDF3 by increasing the amount of nuclear YAP proteins." (PMID 33050646, 2020). "In colorectal cancer tissue samples, the expression of GAS5 was significantly lower than that of adjacent normal tissues." (PMID 32661236, 2020). "If overexpressed, GAS5 can suppress miR-221 expression and subsequently inhibit tumor cell proliferation in colorectal cancer." (PMID 33076450, 2020). "In colorectal cancer, lncRNA GAS5 inhibited the activation of the Wnt/β-catenin signaling pathway, thereby suppressing the angiogenesis, invasion, and metastasis." (PMID 33680941, 2020). "In colorectal cancer, curcumin regulates the tumor suppressor GAS5 to modulate the metastatic pathways." (PMID 32337261, 2020).
colorectal cancer (continued). "In this article, rs145204276 plays an important role in hepatocarcinoma, colorectal cancer, and gastric cancer tissues, and changes the original tumor suppressor effect of GAS5." (PMID 30606744, 2019). "The study found that GAS5 expression was significantly reduced in colorectal cancer tissue samples compared with adjacent healthy tissues." (PMID 30606744, 2019). "Cell experiments revealed that overexpression of GAS5 can significantly inhibit the proliferation rate of colorectal cancer cells, inhibit colorectal cancer cell growth and colony formation, and induce cell cycle G0/G1 arrest and apoptosis." (PMID 30606744, 2019). "This study aims to investigate the effect of long non-coding RNA (lncRNA) Gas5 on proliferation, migration, invasion and apoptosis of colorectal cancer (CRC) HT-29 cell line." (PMID 29308053, 2018). "GAS5 expression was at a low level in five colorectal cancer cell lines, including DLD-1, HCT-116, HT-29, SW620 and SW480, compared with FHC, the normal colon epithelial cells of human." (PMID 28099146, 2017). "The expression profile and underlying mechanism of lncRNA growth arrest specific transcript 5 (GAS5) in colorectal cancer (CRC) is poorly understood." (PMID 28099146, 2017). "Long non-coding RNA GAS5 inhibits cell proliferation, induces G0/G1 arrest and apoptosis, and functions as a prognostic marker in colorectal cancer." (PMID 29340086, 2017). "GAS5 inhibits proliferation and serves as a prognostic indicator in hepatocellular and colorectal cancer." (PMID 27095571, 2016). "Furthermore, one study in human colorectal cancer (CRC) cell lines demonstrated that SNORD80, a snoRNA encoded by a GAS5 intron, can direct the 2′-O-methylation of GAS5." (PMID 40563948, 2025). "Researchers have found through numerous clinical trials that ITGB8-AS1 combined with the corresponding signals can contribute to the growth and metastasis of colorectal cancer and that GAS5 and YAP phosphorylation and degradation interact to inhibit the development of colorectal cancer." (PMID 38233788, 2024). "This study aimed to investigate the effect and mechanism of GAS5 in colorectal cancer." (PMID 36062165, 2022). "Moreover, expression levels of GAS5 were decreased in all examined colorectal cancer cells, as compared to NCM460 normal colon mucosal cells." (PMID 36062165, 2022). "Thus, negatively feedback loop of GAS5-YAP-YTHDF3 is formed to inhibit the progression of colorectal cancer." (PMID 35022030, 2022). "Real-time qPCR was used to detect GAS5 in colorectal cancer cells." (PMID 36062165, 2022). "Indeed, patients with low GAS5 expression exhibited shorter overall survival than those with higher expression and GAS5 expression was an independent indicator of colorectal cancer (CRC) prognosis." (PMID 33483590, 2021). "In addition, a recent study indicated that GAS5 inhibits angiogenesis and metastasis in colorectal cancer by suppressing the Wnt/beta-catenin signaling pathway, which is dedicated to promoting cell invasion and migration in this type of tumor." (PMID 33076450, 2020). "For instance, lincRNA DQ786243 contributed to proliferation and metastasis of colorectal cancer both in vitro and in vivo; GHET1 and TUG1 promoted colon cancer progression; GAS5 contributed to lymphatic metastasis in colorectal cancer; Linc00152 and LincRNA-ROR hold prognostic value." (PMID 31497531, 2019). "GAS5 also plays a role in regulating tumor growth in colorectal cancer." (PMID 30606744, 2019).